FSHR (follicle stimulating hormone receptor)
Diseases named in the same sentence as FSHR in open-access papers (continued):
Sharing a sentence is not in itself a finding about the gene and the disease.
adrenal tumors (1 paper, 2019). "FSHR has been found only by immunohistochemical localization in the intra- and peri-tumoral vessels of adrenal tumors." (PMID 30400009, 2019).
Anosmia (1 paper, 2022). An inability to perceive odors. "It is possible that the anosmia of Kallman syndrome, with unclear etiology, may arise from a dysfunctional FSHR-olfaction circuitry." (PMID 36052994, 2022).
Anxiety (1 paper, 2024). Intense feelings of nervousness, tension, or panic often arise in response to interpersonal stresses. "In summary, our findings revealed that FSHR knockdown alleviates FSH-induced anxiety and depressive behaviors and memory impairment in mice." (PMID 39498265, 2024).
benign lipomas (1 paper, 2015). "In contrast, benign lipomas and the normal fat is FSHR-negative." (PMID 25685198, 2015).
endometrial adenocarcinoma (1 paper, 2021). "We also identified the presence of FSHR in a subgroup of patients with endometrial adenocarcinoma." (PMID 35185785, 2021). "In this study, we employed endometrial adenocarcinoma cells to assess whether FSH/FSHR could activate multiple pathways, and if such activity is regulated at a spatial-temporal level that we and others have demonstrated in heterologous cell lines." (PMID 35185785, 2021).
endometritis (1 paper, 2021). An acute or chronic, usually bacterial infectious process affecting the endometrium. "Although it is difficult to explain this finding, however we assume that the effect on GDF9, StAR, and FSHr expression is associated with clinical endometritis rather than the sub-clinical endometritis." (PMID 33969045, 2021).
epididymis (1 paper, 2015). "While multi unknown factors might increase susceptibility to OA, the results of the present study indicated that single nucleotide polymorphisms in FSHR gene, might account as one of the susceptible factors for the etiology of idiopathic epididymis is obstruction." (PMID 26730241, 2015).
follicular adenomas (1 paper, 2015). "The difference in FSHR expression between follicular cancers and follicular adenomas, as it was shown in the present study, seems to be of importance for a diagnosis." (PMID 25685198, 2015). "The ectopic FSHR immunostaining seems to be useful to differentiate malignant from benign lesions, especially follicular cancers from follicular adenomas." (PMID 25685198, 2015). "The ectopic FSHR immunostaining seems to be useful to differentiate malignant from benign thyroid lesions, especially follicular cancers from follicular adenomas." (PMID 25685198, 2015). "The aim of the study was to re-evaluate the possible usefulness of FSHR immunostaining to differentiate between benign and malignant thyroid lesions, especially between the follicular adenomas and follicular cancers." (PMID 25685198, 2015). "The expression of FSHR may sometimes occur also in the benign thyroid lesions, like thyroid follicular adenomas but that is scarce." (PMID 25685198, 2015). "The ectopic FSHR immunostaining was absent in non-neoplastic thyroid follicles (i.e. the follicles situated outside the tumour) and in the majority (all but two) of follicular adenomas." (PMID 25685198, 2015).
gastric adenocarcinoma (1 paper, 2022). "As additional controls, we used 2 other non-FSHR-expressing cells, AGS gastric adenocarcinoma and WM3743 human melanoma cells, and D2AP11-TCE did not induce off-target toxicities in these 2 cells either." (PMID 36509287, 2022).
Glucose intolerance (1 paper, 2023). Glucose intolerance (GI) can be defined as dysglycemia that comprises both prediabetes and diabetes. "When fed with high-fat diet (HFD), the FSHR KO mice showed aggravated glucose intolerance." (PMID 37914684, 2023).
Gonadotropin deficiency (1 paper, 2012). A reduced ability to secrete gonadotropins, which are protein hormones secreted by gonadotrope cells of the anterior pituitary gland, including the hormones follitropin (FSH) and luteinizing hormone (LH). "FSHR activity enhances Sertoli and spermatogenic development in normal testes, but has limited ability to maintain spermatogenesis during gonadotropin deficiency." (PMID 22558148, 2012).
hemangioblastoma (1 paper, 2025). "FSHR-protein expression was detected in the BV endothelial cells in 100% of VHL-associated CNS-hemangioblastoma, panNET, and ccRCC cases." (PMID 41024941, 2025).
Impaired glucose tolerance (1 paper, 2023). An abnormal resistance to glucose, i.e., a reduction in the ability to maintain glucose levels in the blood stream within normal limits following oral or intravenous administration of glucose. "Previous studies showed that FSH/FSHR mediated the increased fat mass and fat redistribution in postmenopausal women, which may contribute to induce impaired glucose tolerance, indirectly, by decreased insulin sensitivity." (PMID 37914684, 2023).
insulinoma (1 paper, 2023). "FSHR was also identified in mouse pancreatic islets and mouse insulinoma cell line MIN6." (PMID 37914684, 2023).
invasive breast carcinoma (1 paper, 2015). A carcinoma that infiltrates the breast parenchyma. "The observation that in invasive breast cancers the endothelial cells proliferate at the tumor periphery, but not in the interior, suggested that FSHR expression by endothelial cells may be associated with their proliferation in this particular location." (PMID 25652007, 2015).
Iron deficiency (1 paper, 2025). "Iron deficiency arrested mouse estrous cycles at diestrus, blocked secondary follicular development and ovulation due to reduced ovarian ATP levels, downregulation of follicular development markers (FSHR, CYP19A1, CCND2), and decreased estradiol—17β (E2) compared to controls." (PMID 41169787, 2025).
leiomyosarcoma (1 paper, 2013). An uncommon, aggressive malignant smooth muscle neoplasm, usually occurring in post-menopausal women. "We used immunohistochemistry based on a highly FSHR-specific monoclonal antibody to detect FSHR in cancer metastases from 6 major tumor types (lung, breast, prostate, colon, kidney, and leiomyosarcoma ) to 6 frequent locations (bone, liver, lymph node, brain, lung, and pleura) of 209 patients." (PMID 23688201, 2013).
liposarcoma (1 paper, 2015). A usually painless malignant tumor that arises from adipose tissue. "In liposarcomas, FSHR expression was observed in more cases of poorly differentiated than in well differentiated tumours." (PMID 25685198, 2015).
liver cancer (1 paper, 2018). An epithelial or non-epithelial malignant neoplasm that arises from the liver. "The SNV top-ranked SMC3 TFBS motif downstream of FSHR provides a similar example of a previously unknown recurrently mutated TFBS with three liver cancer mutations and three additional SNVs located just outside the element (Fig. 2a14)." (PMID 29354286, 2018).
lymphoma (1 paper, 2025). A malignant (clonal) proliferation of B- lymphocytes or T- lymphocytes which involves the lymph nodes, bone marrow and/or extranodal sites. "Growing evidence indicates that LHR and FSHR are widely distributed in non-reproductive organs and certain tumor tissues, where they are associated with tumor diseases such as lymphoma and mastocytoma." (PMID 40431589, 2025). "Notably, LH receptor (LHR) and FSHR are aberrantly expressed in non-reproductive tumors of spayed dogs, such as lymphoma, splenic hemangiosarcoma, mastocytoma, prostate cancer, and transitional cell carcinoma, and correlate with increased tumor incidence post-gonadectomy." (PMID 40431589, 2025).
metastatic cancer (1 paper, 2019). A carcinoma which has spread from the original site of growth to another anatomic site. "Expression of the follicle-stimulating hormone receptor (FSHR), besides gonadal tissues, has recently been detected in several extragonadal normal and tumorous tissues, including different types of primary and metastatic cancer and tumor vessel endothelial cells (TVEC)." (PMID 30778333, 2019).
neuroblastoma (1 paper, 2025). Neuroblastoma (NB) is the most common solid, extracranial childhood tumor. "FSHR expression has been detected in the human cortex, neuroblastoma cells (SH-SY5Y), mouse cortex, hippocampus, and rat neurons." (PMID 40589620, 2025).
osteoarthritis (1 paper, 2025). A noninflammatory degenerative joint disease occurring chiefly in older persons, characterized by degeneration of the articular cartilage, hypertrophy of bone at the margins and changes in the synovial membrane. "We explored the role of FSH on the synovium and found that FSH was able to mediate the development of osteoarthritis by acting on the FSH receptor (FSHR) to promote the production and release of inflammatory factors through the activation of the NFκB signaling pathway." (PMID 39801258, 2025). "In conclusion, our study was the first to demonstrate that FSHR was expressed in synovial macrophages and that FSH played a proinflammatory role in synovial macrophages, possibly by activating the NFκB pathway to be involved in the pathogenesis of postmenopausal osteoarthritis." (PMID 39801258, 2025).
ovarian epithelial tumor (1 paper, 2017). A benign, borderline, or malignant tumor that originates from the surface epithelium of the ovary. "All ovarian epithelial tumors express FSHR, and the expression level of FSHR is positively correlated with tumor grade." (PMID 28439256, 2017).
ovarian mucinous cystadenocarcinoma (1 paper, 2020). An invasive cystic adenocarcinoma arising from the ovary. "However, other in vitro studies have found that FSHR knockdown was associated with decreased EMT markers in HO8910 and HEY cells, decreased cell proliferation and increased cell apoptosis in human ovarian mucinous cystadenocarcinoma cells." (PMID 33374698, 2020).
pancreatic carcinoma (1 paper, 2023). "In our study, we first examined FSHR expression in human pancreas collected from patients undergoing pancreatic carcinoma surgery." (PMID 37914684, 2023). "In addition, pancreatic tissue from healthy individuals is difficult to obtain, we collected para-carcinoma tissues (non-tumorous normal tissues) from patients undergoing pancreatic carcinoma surgery to detect FSHR expression." (PMID 37914684, 2023).
renal adenocarcinomas (1 paper, 2017). "The pattern of FSH323 staining noticed for ovarian, prostatic, and renal adenocarcinomas indicated that FSHR was expressed mainly in the peripheral tumor blood vessels." (PMID 31548530, 2017).
seizure disorder (1 paper, 2010). "In our cohort, only one subject had a seizure disorder (subject 1), although his 5 Mb deletion encompassed the entire NRXN1 gene as well as the genes for follicle-stimulating hormone receptor (FSHR), luteinizing hormone/choriogonadotropin receptor (LHCGR), and Stoned B-like factor (STN1)." (PMID 20468056, 2010).
temporal lobe epilepsy (1 paper, 2013). A localization-related (focal) form of epilepsy characterized by recurrent seizures that arise from foci within the temporal lobe, most commonly from its mesial aspect. "In normal tissues corresponding to the host organs for the analyzed metastases, obtained from patients not known to have cancer, FSHR staining was absent, with the exception of approx. 1% of the vessels in non tumoral temporal lobe epilepsy samples." (PMID 23688201, 2013).
thyroid tumours (1 paper, 2015). "The recent studies from our and other laboratory showed that the ectopic FSHR immunostaining is also present in thyroid neoplasms." (PMID 25685198, 2015). "However, recently the expression of FSHR was found in tumoral cells and intra-tumoral blood vessels of many other tumours, including thyroid tumours." (PMID 25685198, 2015). "It remains unknown, whether the FSHR protein detectable in thyroid tumours is biologically active." (PMID 25685198, 2015).
uterine corpus leiomyosarcoma (1 paper, 2013). "A highly FSHR-specific monoclonal antibody was used to detect FSHR in cancer metastases from 6 major types of cancers (lung, breast, prostate, colon, kidney, and uterine corpus leiomyosarcoma) to 6 frequent locations (liver, lymph node, bone, pleura, lung, and brain)." (PMID 23688201, 2013).
tumor (66 papers, 2012 to 2025). "FSHR expression in and around blood vessels in different tumors suggests that it is associated with tumor metastasis and neovascularization." (PMID 39741875, 2024). "In this report, we describe the development of monoclonal reagents as tools to target FSHR as a tumor-associated antigen of importance in OC." (PMID 36509287, 2022). "Upregulated endothelial FSHR levels in cancers are associated with vascular remodeling and tumor angiogenesis, whereas, its epithelial counterpart facilitates cell proliferation, migration and invasion." (PMID 35002517, 2022). "Increased FSHR mRNA and protein expression have been linked with low tumor grade in serous carcinomas and reduced overall survival (OS)." (PMID 33374698, 2020). "Using this antibody, we confirmed the presence of FSHR in normal ovary, Fallopian tube and in tumor-associated BVs in HGSOC." (PMID 33374698, 2020). "Our immunohistochemistry study was conducted with the FSHR323 antibody which first reported the expression of FSHR in tumor associated blood vessels." (PMID 33374698, 2020). "In particular, endothelial FSHR expression is associated with vascular remodeling and tumor angiogenesis, whereas epithelial FSHR induces cell proliferation, migration, and cancer cell invasion." (PMID 30941099, 2019). "We have also noticed that blood vessels associated with invasive tumor strands expressed also the endothelial FSHR." (PMID 25652007, 2015). "Moreover, high FSHR expression in tumor cells and tumor vasculature was associated with a longer progression-free survival and overall survival." (PMID 40722863, 2025). "FSHR expression is associated with a range of tumor types, such as gastrointestinal tumors, and it is not detected in healthy tissues located more than 10 mm from the tumor site or in tumor lymphatics." (PMID 37568488, 2023). "Elevated FSHR expression on tumor endothelial cells could serve as a diagnostic factor and predictor of response to angiogenesis-inhibiting treatment, particularly in tumors with increased angiogenesis and growth factor association." (PMID 37568488, 2023). "The molecular mechanism underlying FSHR-dependent tumor angiogenesis and vascular remodeling could involve hypoxia-inducible factor 1α and the vascular endothelial growth factor (VEGF) pathway, as observed in ovarian granulosa cells." (PMID 37375761, 2023). "Blood vessels associated with invasive tumor cell strands expressed also the endothelial FSHR." (PMID 25652007, 2015). "Notably, that study showed that FSHR expression occurred exclusively on the endothelial cells of blood vessels, not lymphatic vessels, which may be associated with the spread of the tumor through the bloodstream." (PMID 37568488, 2023). "FSHR protein and mRNA levels have been reported in tumor vessel endothelial cells of the human prostate and LNCaP xenograft vessels (of murine origin)." (PMID 40490708, 2025). "FSHR is expressed in tumor vessel endothelial cells in the prostate, breast, colon, pancreas, urinary bladder, kidney, lung, liver, stomach, testis, and ovary, as well as in metastases." (PMID 40490708, 2025). "Although FSHR-positive tumor vessel endothelial cells were previously reported in LNCaP cell xenografts, we were unable to reproduce FSHR expression." (PMID 40490708, 2025). "A novel variant of the lytic peptide phor, composed of 18 amino acids (Phor18) conjugated to FSHβ has been shown to inhibit the growth of PC-3 xenografts by targeting FSHR-expressing cancer or endothelial cells of tumor vessels." (PMID 40490708, 2025). "Extragonadal follicle-stimulating hormone receptor (FSHR) expression at low levels has been shown in several normal and tumor tissues, including myometrium and adipose tissue." (PMID 39633277, 2024). "Targeted immunotherapy against FSHR has achieved significant breakthroughs, including TCE, NKCE, and novel DNA vaccines, which can help in OC treatment and prevent tumor recurrence after the first-line treatment of FSHR+ tumors." (PMID 39741875, 2024).
tumor (continued). "FSHβ 33–53 and FSHβ 81–95 peptides promote paclitaxel-loaded NP entry into the FSH receptor (FSHR)-positive ovarian tissue to achieve excellent anti-tumor effects." (PMID 38675151, 2024). "This SynCon DNA vaccine targeting FSHR broke immune tolerance, elicited potent long-lasting CD8+ and CD4+ responses, and delayed FSHR+ tumor progression by enhancing antitumor immunity, specifically CD8+ cytotoxic T lymphocyte (CTL) responses." (PMID 39741875, 2024). "The peripheral positioning of vessels expressing FSHR in a tumor presents a potential target for treatment." (PMID 37568488, 2023). "It has been found that in numerous tumors, FSHR expression stimulates proliferation and metastasis, while vascular endothelial FSHR promotes tumor angiogenesis and blood vessel remodeling." (PMID 37568488, 2023). "Within the epithelium, FSHR plays a role in the proliferation, migration, and invasion of tumor cells." (PMID 37568488, 2023). "FSHR expression was also described among tumor metastases arising from six different primary tumors (lung, breast, prostate, colon, kidney, and leiomyosarcoma) suggesting a role in the migration and invasion of cancer cells." (PMID 37375761, 2023). "Studies using FSHR expression to determine tumor infiltration depth indicated successful tumor resections for lesions that were <20 mm, avoiding a supplementary hemicolectomy without additional risk factors." (PMID 37568488, 2023). "Targeting of diverse populations of OC and the ability to complement currently available tools for treatment of this disease support study in additional FSHR-positive tumor models." (PMID 36509287, 2022). "We have recently reported the potential for tumor impact, tolerability, and safety of targeting FSHR by vaccination using an immunocompetent mouse model." (PMID 36509287, 2022). "The function and regulation of FSH and FSHR interaction have been studied mainly using invivo models and primary cells, as well as tumor and immortalized cell lines overexpressing FSHR." (PMID 35471239, 2022). "We expressed murine FSHR in mouse tumor lines A20 and ID8-Defb29/Vegf-a and again tested binding of D2AP11 to transfected and untransfected cells by flow cytometry." (PMID 36509287, 2022). "Few groups have also confirmed FSHR by Western blotting in tumor tissues and reported multiple alternately spliced isoforms." (PMID 34717708, 2021). "FSHR has also been found to be selectively expressed on the surface of many tumor blood vessels, and related to tumor metastasis." (PMID 34717708, 2021). "Numerous studies have reported the aberrant expression of FSHR in various tumor cells and peripheral tumor blood vessels." (PMID 33716953, 2020). "In the current study, we found that both phospho-SphK1 and phospho-SphK2 were significantly correlated with the FSHR level in tumour tissue." (PMID 32796926, 2020). "An additional difference was detected in TD_549, where one copy of FSHR has translocated to chromosome 1 but both copies of this gene are located on the short arm of chromosome 2 in the other three tumour cell lines." (PMID 32354058, 2020). "Recent studies have suggested the expression of FSHR in many normal extragonadal tissues, as well as in the tumors and tumor vessel endothelial cells (TVECs)." (PMID 30778333, 2019). "Ubiquitous expression of FSHR on various adult organs and tumor tissues possibly reflects novel VSELs biology." (PMID 30241552, 2018). "The KGN cell line is a steroidogenic human ovarian granulose-like tumor cell line considered a very useful model for researching steroidogenesis, cell growth and FSHR-coupled signaling pathways in human granulosa cells." (PMID 28282971, 2017). "In terms of subcellular localization, the observed FSHR staining was pre-dominantly cytoplasmic, whereas the plasma membrane was only stained in single tumor cells." (PMID 31548530, 2017).